SRF (serum response factor)
Diseases named in the same sentence as SRF in open-access papers (continued):
Sharing a sentence is not in itself a finding about the gene and the disease.
epilepsy (continued). "Although the transcription factor serum response factor (SRF) has been suggested to play a role in activity-dependent gene expression and mediate plasticity-associated structural changes in the hippocampus, no unequivocal evidence has been provided for its role in brain pathology, such as epilepsy." (PMID 25636686, 2016). "Thus, SRF might team-up with these two gene regulators for epilepsy mediated gene regulation." (PMID 28716058, 2017). "In a subset of patients however, we did not observe differential SRF RNA expression between the epilepsy and non-epilepsy subgroups by qRT-PCR." (PMID 30621209, 2019). "Thus, regardless of the epilepsy-inducing agent, SRF emerges as important regulator of SRS activity." (PMID 28716058, 2017). "Thus, the lack of these effector proteins in SRF knockout animals may lead to uncontrolled excitation and eventually epilepsy." (PMID 25636686, 2016).
Obesity (4 papers, 2020 to 2025). Accumulation of substantial excess body fat. "At the cellular level transcriptional actions of EGFR were potentiated by glucose and pathway analysis identified the serum response factor (SRF) as an activated vascular transcription regulator during T2DM/obesity." (PMID 41429904, 2025). "Thus, a clock–actin–MRTF/SRF regulatory pathway may also function in classical WAT to modulate fibrotic changes that could be applicable to obesity or clock disruption-related metabolic diseases." (PMID 36581314, 2023). "Key genes within locus 6.52, including VEGFA, SRF, and GNMT, established a link between obesity and chronic ischemic heart disease." (PMID 40565603, 2025). "While MRTF/SRF suppresses beige adipogenesis, recent studies further demonstrated that MRTF/SRF activity was induced in HFD-induced obesity, promoting an adipogenic progenitor fate switch to fibrogenic lineage that predisposes to adipose fibrosis." (PMID 36581314, 2023). "Thus, SRF represents a potential integration hub of EGFR and glucose-induced signalling during obesity/type 2 diabetes." (PMID 32548701, 2020). "We show that VSM-EGFR mediates obesity/type 2 diabetes-induced vascular dysfunction, remodelling and transcriptome dysregulation preceding renal damage and identify an EGFR–glucose synergism in terms of SRF activation, matrix dysregulation and mitochondrial function." (PMID 32548701, 2020).
rhabdomyosarcoma (4 papers, 2021 to 2025). A rare aggressive malignant mesenchymal neoplasm arising from skeletal muscle. "Spindle cell/sclerosing rhabdomyosarcomas typically harbor certain genomic alterations, including rearrangements involving TFCP2, VGLL2, NCOA2, CITED2, TEAD1, and SRF, as well as the MYOD1 p.L122R mutation." (PMID 40361368, 2025). "The involvement of SRF in different rearrangement events has been identified in various soft tissue tumor types, as in perivascular myoid tumors and rhabdomyosarcomas." (PMID 36421692, 2022). "Moreover, SRF::NCOA2 fusion-positive pediatric RMS (rhabdomyosarcoma) showing diffuse staining for desmin and multifocal nuclear positivity for myogenin are reported." (PMID 36421692, 2022).
aneurysm (3 papers, 2017 to 2026). Bulging or ballooning in an area of an artery secondary to arterial wall weakening. "Moreover, while KO of MYOCD in SMCs results in aortic aneurysms with dissection and rupture, aneurysm propensity in SRF-deficient mice has not been examined." (PMID 40081573, 2025). "Indeed, we find that some hallmarks of aneurysmal disease develop spontaneously when SRF is depleted from vascular SMCs in young mice, suggesting that SRF depletion may contribute to some of the prodromal stages of aneurysm formation." (PMID 40081573, 2025). "In summary, through the integration of single-nucleus multi-omics, SRF ChIP-seq, and rigorous wet lab validation, we comprehensively delineated the major transcriptional effectors regulated by MAPK14, a key upstream signaling molecule that facilitates VSMC degeneration and aneurysm formation." (PMID 41526342, 2026).
Arrhythmia (3 papers, 2018 to 2022). Any cardiac rhythm other than the normal sinus rhythm. "Moreover, SRF may be closely related to cardiac disease and arrhythmia, raising the new question whether SRF may be a candidate for the missing link passing on the effects of chronic distress to the regulation of miR-1 expression." (PMID 36077591, 2022). "This suggested that SRF might play an important role in arrhythmia events." (PMID 34646152, 2021). "To this end, we determined the effects of the sEHI trans-4-[4-(3-adamantan-1-yl-ureido)-cyclohexyloxy]-benzoic acid (t-AUCB) on the expression of miR-133, its target arrhythmia–related genes (KCNQ1 and KCNH2), and serum response factor (SRF), an important transcriptional factor in cardiomyocytes." (PMID 29843720, 2018).
autism spectrum disorder (3 papers, 2019 to 2023). A spectrum of developmental disorders that includes autism, and Asperger syndrome. "Association of the MKL/SRF pathway was also reported with autism spectrum disorders, which involve early brain malformations including defects in neurogenesis and migration." (PMID 37967194, 2023).
coronary artery disease (3 papers, 2015 to 2025). "Moreover, SRF-myocardin axis has been shown to be antagonized by the over-expression of the coronary artery disease-risk gene Tcf21 in vivo." (PMID 41246212, 2025).
deep vein thrombosis (3 papers, 2016 to 2023). "Moreover, miR-483-3p is upregulated in endothelial progenitor cells (EPC) from deep vein thrombosis (DVT) patients and targets the serum response factor (SRF) to decrease EPCs migration and tube development, concomitantly to the increased rate of the apoptotic cells." (PMID 29867024, 2018).
diabetes (3 papers, 2023 to 2025). "In addition, in the diabetes rat model, high glucose induces the upregulation of miR-1-3p in cardiomyocytes through the MEK1/2 pathway and serum response factor (SRF) and then promotes cardiomyocyte apoptosis by targeting HSP60." (PMID 37907984, 2023). "While our data suggests a putative crosstalk between YY1/SRF-related mechanisms and OGT-mediated VSMC de-differentiation, additional studies are warranted to elucidate the molecular pathways that link OGT to YY1 and SRF in regulation of VSMC phenotypic transformation in diabetes." (PMID 37175604, 2023).
diabetic nephropathy (3 papers, 2019 to 2026). "It has been shown that SRF is closely correlated to renal fibrosis in diabetic nephropathy and plays an important role in EMT in many types of renal cells, such as podocytes, TECs and glomerular endothelial cells." (PMID 31774735, 2019).
dilatation (3 papers, 2017 to 2025). "We also confirmed that voluntary exercise could stabilize the systolic function in SRF-deficient transgenic mice, although the ventricular dilatation in diastole still takes place." (PMID 29187823, 2017). "Our findings argue that testing of the role of the SRF regulon in aneurysmal disease in young mice may require complicated neutralization of adaptive changes involving YAP/TAZ target genes, including Ctgf, Lox, and Serpine1 in i8-SRF-KO aorta." (PMID 40081573, 2025). "We mimicked one aspect of these changes by genetic SRF depletion in young mice, impairing contractility and eliciting aortic remodeling and MEMA, which are hallmarks of aneurysmal disease." (PMID 40081573, 2025). "Taken together, this experiment argues that attrition of the SRF regulon in young mice does not accelerate aneurysmal disease in an experimental design that minimizes time for compensatory changes (that are driven in part by YAP/TAZ)." (PMID 40081573, 2025). "Moreover, a model generated to mimic suppression of the SRF regulon in young mice (avoiding other age-dependent changes), featured outward aortic remodeling and MEMA that are cardinal features of aneurysmal disease." (PMID 40081573, 2025).
endothelial dysfunction (3 papers, 2015 to 2021). In vascular diseases, endothelial dysfunction is a systemic pathological state of the endothelium (the inner lining of blood vessels) and can be broadly defined as an imbalance between vasodilating and vasoconstricting substances produced by (or acting on) the endothelium. "A possible explanation could be the expression of transcription factors, such as serum response factor (SRF) and mammalian target of rapamycin (mTOR), which are critical regulators in vascular ECs and are associated with endothelial dysfunction." (PMID 33317046, 2020). "In endothelial cells, SRF is essential for VEGF‐induced cell signaling and angiogenesis, and thus endothelial dysfunction." (PMID 34185408, 2021). "Moreover, induced by SP1, miR-320a downregulated SRF, a key endothelial cell regulator essential for VGEF induced cell signalling and angiogenesis, and contributed to endothelial dysfunction." (PMID 25728840, 2015).
fibrosis (3 papers, 2017 to 2025). the formation of excess fibrous connective tissue in an organ or tissue in a reparative or reactive process. "For example, CCG-222740 is reported to be five times more potent than CCG-203971 in inhibiting MRTF/SRF target genes and effectively reduces scar tissue formation in fibrosis models while exhibiting lower cytotoxicity than earlier inhibitors do." (PMID 39996739, 2025).
gastric ulcer (3 papers, 2011 to 2021). An ulcerated lesion in the mucosal surface of the stomach. "SRF has potential healing benefits in gastric ulcers, and our result showed weak SRF up-regulation predisposes to increased risk of recurrent gastric ulcer bleeding." (PMID 21410985, 2011). "Weak SRF up-regulation, combined with the presence of co-morbidities, increase the risk of the recurrent gastric ulcer bleeding." (PMID 21410985, 2011). "Combining both factors, the risk of recurrent gastric ulcer bleeding in co-morbid patients with weak SRF up-regulation increased by 8.29-fold (95% CI, 1.31~52.62; p = 0.03)." (PMID 21410985, 2011). "The weak up-regulation of SRF on ulcer tissues and the presence of co-morbidities independently increase the risk of recurrent gastric ulcer bleeding." (PMID 21410985, 2011). "We also examined the role of SRF in gastric ulcer healing by locally injecting an SRF expression plasmid into the GU base." (PMID 34440733, 2021). "Multivariate logistic regression confirmed that co-morbidities and weak SRF up-regulation were two independent factors of recurrent gastric ulcer bleeding (p < 0.05)." (PMID 21410985, 2011). "Data here corroborates the assessment of SRF expression in gastric ulcer tissues as meaningful and important in identifying a subset of patients who carry higher risk of recurrent bleeding." (PMID 21410985, 2011). "Ulcer and non-ulcer tissues were obtained from 142 patients with active gastric ulcers for SRF expression assessed by immunohistochemistry." (PMID 21410985, 2011). "SRF reportedly promotes gastric ulcer healing by stimulating the proliferation and differentiation of such cells." (PMID 21410985, 2011). "As H. pylori infection and NSAID use are the two major leading etiologies of gastric ulcers, assessing the up-regulation of SRF can be widely applied for most patients." (PMID 21410985, 2011). "The study determined if gastric ulcer tissues up-regulate SRF and if such up-regulation correlated with co-morbidities and the risk of recurrent bleeding." (PMID 21410985, 2011). "Patients with weak SRF up-regulation in ulcer tissues have significantly higher rates of Forrest classification Ia to IIc SRH in gastric ulcers (p < 0.01) and this trend becomes more common with co-morbid illnesses (p = 0.14)." (PMID 21410985, 2011). "Additionally, a local therapy with VEGF plus angiopoietin 1 cDNAs or with serum response factor (SRF) plasmid dramatically accelerates gastric ulcer healing and improves the quality of mucosal restoration within ulcer scars." (PMID 34440733, 2021). "SRF, a transcription factor, also plays important roles in gastric ulcer healing." (PMID 34440733, 2021). "The molecular events in granulation tissue that contribute to the mechanisms of gastric ulcer healing include the activation of genes encoding bFGF, FGF-R1,2,4, VEGF, and flk-1/KDR; Ang 1 and Ang 2; Tie 2 receptor; COX-2; SRF; NGF; SDF-1; and BMD-EPC via the activation of PI3K/Akt pathway." (PMID 34440733, 2021). "SRF not only promotes the differentiation of myofibroblast from other cells including fibroblasts through trans-differentiation, but also plays an important role in the formation of granulation tissue during the healing of rat gastric ulcers." (PMID 27323859, 2016). "For such patients, more aggressive bleeding control such as applying long term oral PPI or improving the weak up-regulation of SRF on gastric ulcers may be mandatory." (PMID 21410985, 2011). "In summary, gastric ulcer tissues exert different degrees of SRF up-regulation." (PMID 21410985, 2011). "The possible reasons may be whatever the etiology of gastric ulcers is, SRF is triggered and activated by wounding." (PMID 21410985, 2011). "Nevertheless, our study showed SRF expression on gastric ulcers is not different between patients with H. pylori infection and NSAID users." (PMID 21410985, 2011). "Gastric ulcer tissues had higher SRF expression than non-ulcer tissues (p < 0.05)." (PMID 21410985, 2011).
gastric ulcer (continued). "SRF expression is higher in gastric ulcer tissues than in non-ulcer tissues." (PMID 21410985, 2011). "This study aimed to determine whether SRF expression in gastric ulcer tissues is higher than that of antral non-ulcer tissues, and if SRF expression in gastric ulcer tissues is related to Helicobacter pylori (H. pylori) infection, non-steroidal anti-inflammatory drugs (NSAID) intake, or others." (PMID 21410985, 2011).
leiomyosarcoma (3 papers, 2015 to 2023). An uncommon, aggressive malignant smooth muscle neoplasm, usually occurring in post-menopausal women. "In human uterine leiomyosarcoma cells, myocardin in conjunction with SRF directly binds to the p21 promoter and induces its expression, thus resulting in G1/S arrest." (PMID 25888165, 2015). "By integrating large-scale data, we identified two specifically deregulated pathways involved in differentiation/proliferation switch (MYOCD/SRF and E2F1/RB1) in a subgroup of well-differentiated vascular smooth muscle cell-derived cells leiomyosarcomas." (PMID 36672483, 2023).
muscular dystrophy (3 papers, 2014 to 2018). Muscular dystrophy (MD) refers to a group of more than 30 genetic diseases characterized by progressive weakness and degeneration of the skeletal muscles that control movement. "Therefore, mutations in the actin protein lead to alterations in the SRF pathway that could promote muscle cell degeneration and cause myopathy or muscular dystrophy." (PMID 29506508, 2018).
neuroblastoma (3 papers, 2014 to 2017). Neuroblastoma (NB) is the most common solid, extracranial childhood tumor. "CRA-CM increased the expression of SRF in human neuroblastoma SH-SY5Y cells, an established model for human brain cells." (PMID 29109537, 2017). "SRF shows broad-spectrum activity as it effectively inhibits proliferation of several different cancer cell types derived from solid tumors and hematological malignancies, as well as neuroblastomas and drug-resistant." (PMID 25354194, 2014).
abdominal aortic aneurysm (2 papers, 2024). Enlargement and ballooning of the vessel that supplies arterial blood to the abdomen, pelvis and legs. "Recent studies have shown that TCF7L1 (transcription factor 7-like 1) reduces the transcriptional activity of SRF and promotes the phenotypic transformation of VSMC, which aggravates the formation of abdominal aortic aneurysm." (PMID 38913045, 2024).
acute leukemia (2 papers, 2023 to 2024). A clonal (malignant) hematopoietic disorder with an acute onset, affecting the bone marrow and the peripheral blood. "The canonical signalling pathway upstream of SRF is the RhoGTPase–actin–megakaryotic acute leukemia (MAL) axis." (PMID 37385752, 2023).
arterial disease (2 papers, 2016 to 2025). "Given the long-term viability, these knockouts can probably be aged to determine effects of SRF depletion on arterial disease in the setting of old age." (PMID 40081573, 2025). "In fact, many YAP targets, including transcriptional coactivator with PDZ-binding motif (TAZ), TEAD family transcription factors, and the myocardin-SRF complex, have been studied in the context of other arterial diseases." (PMID 27608489, 2016).
autism (2 papers, 2016 to 2023). Persistent deficits in social interaction and communication and interaction as well as a markedly restricted repertoire of activity and interest as well as repetitive patterns of behavior. "Interestingly, mutations in those SRF targets have found to be associated with such human neuropsychiatric disorders, as autism and intellectual disability." (PMID 25636686, 2016). "Similarly, depletion of the enriched transcription factor SRF during early life contributes to autism-like deficits in social interaction in adulthood and neurodevelopmental disorders." (PMID 37851674, 2023).
breast invasive carcinomas (2 papers, 2019 to 2023). "In line with a role in tumour suppression, SRF levels are significantly reduced in invasive breast cancer compared with control normal tissues (Wilcoxon P = 1.164e−20)." (PMID 31414556, 2019). "Additionally, breast invasive carcinomas (TCGA) display higher SRF mRNA expression in tumours with high levels of RASSF1A transcript (P < 0.0001), which also shows significant linear correlation across the dataset (R = 0.28)." (PMID 31414556, 2019).
chronic obstructive pulmonary disease (2 papers, 2013 to 2023). A chronic and progressive lung disorder characterized by the loss of elasticity of the bronchial tree and the air sacs, destruction of the air sacs wall, thickening of the bronchial wall, and mucous accumulation in the bronchial tree.
conotruncal heart defect (2 papers, 2020 to 2022). "A recent study performed targeted sequencing of SRF in nonsyndromic conotruncal heart defect patients and identified two novel mutations with reduced transcriptional output, one from a patient with VSD and the other with Tetralogy of Fallot with right aortic arch." (PMID 35044299, 2022).
COVID-19 (2 papers, 2022 to 2023). A disease caused by infection with severe acute respiratory syndrome coronavirus 2. "Notably, the SRF gene demonstrated a unique and dysfunctional pattern in COVID-19." (PMID 36913345, 2023). "In COVID-19 interaction, the TF–miRNA network showed that E2F1, MAX, EGR1, YY1, and SRF were the highly expressed TFs, and hsa-miR-19b, hsa-miR-495, hsa-miR-340, hsa-miR-101, and hsa-miR-19a were among significant miRNAs." (PMID 36059456, 2022). "In COVID-19 patients, the DEG–miRNA, and DEG–transcription factors (TFs) interactions network analysis revealed that E2F1, MAX, EGR1, YY1, and SRF were the highly expressed TFs, whereas hsa-miR-19b, hsa-miR-495, hsa-miR-340, hsa-miR-101, and hsa-miR-19a were the overexpressed miRNAs." (PMID 36059456, 2022).
dengue (2 papers, 2016 to 2022). "It is proposed that NF-AT, SRF, and VDR may be involved in the regulation of immune response against dengue-mediated hypovolemic shock." (PMID 27038471, 2016).
exudative vitreoretinopathy (2 papers, 2014 to 2021). Familial exudative vitreoretinopathy (FEVR) is a rare hereditary vitreoretinal disorder characterized by abnormal or incomplete vascularization of the peripheral retina leading to variable clinical manifestations ranging from no effects to minor anomalies, or even retinal detachment with blindness. "The murine phenotypes upon post-natal endothelial depletion of SRF or MRTF-A/-B reflect some pathological features exhibited by human patients suffering from FEVR (familial exudative vitreoretinopathies) and AMD (adult macular degeneration)." (PMID 25203538, 2014).